FUS (FUS RNA binding protein)
Diseases named in the same sentence as FUS in open-access papers (continued):
Sharing a sentence is not in itself a finding about the gene and the disease.
sarcoma (continued). "Although these sarcomas have variable cell phenotypes, transcriptomes, prevalence, and prognoses, they are all driven by FUS, EWSR1, or TAF15 (sometimes referred to as the ‘FET’ gene family) fused to a transcription factor." (PMID 33669307, 2021). "These proteins are fused in sarcoma (FUS), heterogeneous nuclear ribonucleoprotein A1 (hnRNPA1), and the TAR DNA-binding protein 43 (TDP-43)." (PMID 34762868, 2021). "These proteins include the microtubule-associated protein tau, the transactive response DNA binding protein molecular weight 43 (TDP-43), fused in sarcoma (FUS), Ewing’s sarcoma (EWS) or TATA-binding protein-associated factor 15 (TAF15)." (PMID 34858989, 2021). "We first demonstrate reduced nuclear-to-cytoplasmic ratios of transactive response DNA-binding protein 43 (TDP-43), fused in sarcoma/translocated in liposarcoma (FUS) and splicing factor proline and glutamine rich (SFPQ) in VCP mutant motor neurons." (PMID 34396115, 2021). "The results showed that fused in sarcoma (FUS), aconitase 1 (ACO1), and YTH domain containing 1 (YTHDC1) motifs have specific miR-18b binding sites." (PMID 34853307, 2021). "FUS (fused in sarcoma) is present in pathological aggregations with a lower percentage than TDP-43 and its association and effects on SGs have been studied." (PMID 34248597, 2021). "Nevertheless, a number of such mutations have been reported, e.g., in the genes coding for the RNA-binding proteins FUS (fused in sarcoma) and TDP-43 (TAR DNA- binding protein 43)." (PMID 34948065, 2021). "The results showed that human amino-terminal enhancer of split (AES, a corepressor gene of RELA) RNA expression was markedly elevation, but fused in sarcoma (FUS, a coactivator gene of RELA) RNA expression was suppressed dramatically in the HK2-Six1 cells." (PMID 34513929, 2021). "In leukemia cells, USP15 interacts with and stabilizes FUS (fused in sarcoma), a known DNA repair factor, directly linking USP15 to the DNA damage response (DDR)." (PMID 33378683, 2020). "USP15 had a positive role in preserving normal stem and leukemic cell genome integrity and mediated the stability of a HSC self-renewal and DNA repair factor, FUS (fused in sarcoma)." (PMID 33378683, 2020). "This translocation is also commonly referred to as FUS-DDIT3, where FUS (fused in sarcoma) corresponds to TLS and DDIT3 (DNA damage inducible transcript 3) represents CHOP." (PMID 32344731, 2020). "The RNA-binding protein FUS (fused in sarcoma) was identified as the most likely HEAL cofactor based on the number of enriched peptides present in HEAL versus lacZ samples." (PMID 31551335, 2019). "Using in vivo electroporation with CRISPR/Cas9 technology, we also generated a spatially and temporally restricted FUS-CHOP-driven sarcoma model that forms with high penetrance." (PMID 31427882, 2019). "We successfully generated sarcomas in mice that are driven by FUS-CHOP, recapitulate the “crow's feet” vasculature of human MLPS histologically, and resemble high-grade soft tissue sarcomas." (PMID 31427882, 2019). "This difference indicates that FUS-CHOP expression contributes to the development of sarcomas in mice." (PMID 31427882, 2019). "We also employ in vivo electroporation and CRISPR technology to rapidly generate spatially and temporally restricted mouse models of high-grade FUS-CHOP-driven sarcomas for preclinical studies." (PMID 31427882, 2019). "Here, we report the generation and characterization of a spatially and temporally restricted mouse model of sarcoma driven by FUS-CHOP." (PMID 31427882, 2019).
sarcoma (continued). "In summary, we report the generation of multiple conditional mouse models of FUS-CHOP-driven sarcoma and show that Prrx1-expressing cells are a potential source of myxoid liposarcoma." (PMID 31427882, 2019). "Here, we generated and characterized multiple genetically engineered mouse models of FUS-CHOP-driven sarcoma to dissect the molecular events required for sarcomagenesis in vivo." (PMID 31427882, 2019). "Fused in sarcoma: DNA damage‐inducible transcript 3 protein (FUS:DDIT3) is a chimeric fusion oncoprotein present in 90% of human myxoid liposarcomas (MLS)." (PMID 30979710, 2019). "Translocation of CREB3L2 gene, located on chromosome 7, and the FUS gene (fused in sarcoma) located on the chromosome 16 has been found in some tumors, including skin cancer and soft tissue sarcoma." (PMID 30940212, 2019). "FUS is a member of the Ewing’s sarcoma family of proteins that appears to translocate from the cytoplasm to the nucleus, and it is phosphorylated in response to radiotherapy." (PMID 29866190, 2018). "RNA-binding protein immunoprecipitation assay (RIP) and RNA pulldown were used to confirm the binding of LINC00470 and fused in sarcoma (FUS)." (PMID 29866190, 2018). "Between 5-10% of these have FUS protein deposits (fused in sarcoma) and 70% of cases of PNFA show tau protein deposits, whereas 30% display accumulation of TDP-43 protein." (PMID 29213521, 2017). "These were based on fusions of an IDR derived from the RNA granule protein FUS (fused in sarcoma) to a multivalent poly-Src homology 3 (SH3) domain protein that phase-separates when mixed with a poly-proline–rich-motif (polyPRM) ligand." (PMID 28924037, 2017). "In 11 patients, six had phosphorylated TAR DNA-binding protein 43 (pTDP-43)-immunoreactive (ir) neuronal cytoplasmic inclusions (NCI), two had fused in sarcoma (FUS)-ir NCI, and three had copper/zinc superoxide dismutase (SOD1)-ir NCI." (PMID 27716404, 2016). "Of particular interest in this category was the decreased expression of the FALS-associated nucleo-cytoplasmic shuttling RNA binding protein fused in sarcoma (FUS −1.79), which is involved in RNA splicing and regulation of transcription." (PMID 24750211, 2015). "•Is RNP assembly regulated by post-translational modifications of RBPs, for example phosphorylation, as was suggested for the RBP FUS (fused in sarcoma)?" (PMID 25012293, 2014). "FET family proteins consist of fused in sarcoma/translocated in liposarcoma (FUS/TLS), Ewing's sarcoma (EWS), and TATA-binding protein-associated factor 15 (TAF15)." (PMID 24804206, 2014). "For example, FUS (fused in sarcoma) was initially classified as a fusion oncogene in human myxoid liposarcomas, and later implicated in Mendelian neurodegeneration through the identification of germline mutations in familial amyotrophic lateral sclerosis." (PMID 24456803, 2014). "The last group of hnRNPs found in maintenance of stem cell self-renewal and development potency is RNA binding protein EWS (Ewing sarcoma breakpoint 1, also called EWSR1) and FUS (fused in sarcoma, also called TLS/hnRNP P2)." (PMID 23984388, 2013). "A major genetic network contains known cancer-related or pro-proliferating genes, including CDC25A, CDK19, FUS (fused in sarcoma), TLE3, and ILF3 (interleukin enhancer binding factor 3) was formed." (PMID 24160375, 2013). "Previous ALS mouse models include ones involving the SOD1, TDP-43 as well as the DNA/RNA binding proteins FUS (fused in sarcoma) genes." (PMID 23029473, 2012). "Interphase FISH analysis for rearrangement of the EWSR1 and FUS loci was successfully performed in two of the three cases of myoepithelioma-like sarcoma." (PMID 22588017, 2011). "To determine whether LMNs with ALS mutations exhibit pathological phenotypes, we used four ALS-iPSC lines carrying genetic mutations in either TDP-43 (TARDBP, TAR DNA binding protein 43) or FUS (fused in sarcoma)." (PMID 39706179, 2025).
sarcoma (continued). "Furthermore, PTH1R, encoding the parathyroid 1 receptor, was also highly expressed in FUS/EWSR1-TFCP2 sarcomas and strongly induced by TFCP2 fusions in immortalized cells." (PMID 38168093, 2024). "To date, two patients with FUS/EWSR1-TFCP2 sarcoma who received ALK inhibitors have been reported." (PMID 38168093, 2024). "Importantly, we identified the runt-related transcription factor 1 (RUNX1) and RNA-binding proteins (RBPs) fused in sarcoma (FUS) protein and recombinant ELAV-like protein 1 (ELAVL1) as mediators of circPTPN22 biogenesis." (PMID 38956466, 2024). "In summary, the differential diagnosis of EWSR1/FUS::NFATC2 sarcoma is complex with many pitfalls." (PMID 38254207, 2024). "The protein EWS1 (Ewing’s sarcoma breakpoint region 1) along with the gene products encoded by FUS (fused in sarcoma)/TLS (translocated in liposarcoma) and the TATA box binding associated factor 15 (Taf15), are RNA and DNA binding proteins that belong to the FET (FUS, EWS, TAF15) family of proteins." (PMID 38653846, 2024). "Additionally, runt-related transcription factor 1 (RUNX1) negatively regulates circPTPN22 expression, while RNA-binding proteins such as FUS (fused in sarcoma) and ELAVL1 (recombinant ELAV-like protein 1) positively regulate its expression." (PMID 38956466, 2024). "One study demonstrated that USP15 could interact with and stabilize a known DNA repair factor called FUS (fused in sarcoma) in hematopoietic stem cells and leukemia cells." (PMID 39522000, 2024). "In addition, extraskeletal myxoid chondrosarcoma (EMC) needs to be differentiated from EWSR1/FUS::NFATC2 sarcoma." (PMID 38254207, 2024). "Furthermore, in CML cells, USP15 interacts with and increases the stability of FUS (fused in sarcoma), a well-known factor involved in DNA repair." (PMID 39048945, 2024). "FISH and NGS play an important role in the diagnosis of EWSR1/FUS::NFATC2 sarcoma." (PMID 38254207, 2024). "The fusion breakpoints and fusion types in EWSR1/FUS::NFATC2 sarcoma may impact the tumor's biological behavior and prognosis." (PMID 38254207, 2024). "The FUS-CHOP oncoprotein has been shown to induce metastasis in an in vivo model of sarcoma." (PMID 37685841, 2023). "These mainly comprise EWSR1::NFATC2 and FUS::NFATC2 sarcomas and EWSR1::PATZ1 sarcomas." (PMID 36941503, 2023). "Immunohistochemically, CD99 is diffusely expressed in 50% of EWSR1/FUS::NFATC2 sarcoma cases." (PMID 36983010, 2023). "Western blot, co-focus, and RIP assay were used to verify the direct interaction between MIR137HG and FUS (fused in sarcoma/translocated in liposarcoma, FUS/TLS), while dual-luciferase reporter assay was used to confirm the interaction between miR-2682-3p and FUS." (PMID 35733138, 2022). "In addition, more recently, RBPs such as transactive response DNA-binding protein 43 (TDP-43) and fused in sarcoma (FUS) related to neurodegenerative diseases have been shown to undergo liquid-liquid phase separation (LLPS)." (PMID 35822056, 2021). "Finally, an RBP that is potentially involved in both DSB signaling and repair is the hnRNP FUS (fused in sarcoma, also known as TLS and hnRNP P2), which has pleiotropic functions in transcription, RNA metabolism, and genome maintenance." (PMID 34026839, 2021). "Notably, SIX1 targeted the promoters of the amino-terminal enhancer of split (AES) and fused in sarcoma (FUS), which are cofactors of nuclear factor-κB (NF-κB) subunit RELA, and then inhibited the transactivation function of RELA." (PMID 34513929, 2021). "As expected, NMR analysis of the methylation-free recombinant RG/RGG model proteins cold-inducible RNA-binding protein (CIRBP) and RNA-binding protein fused in sarcoma (FUS) revealed that ADMA and MMA are detectable in recombinant proteins after incubation with PRMT1 and the methyl donor SAM." (PMID 35475236, 2021). "Because different sarcomas subtypes appear to arise from different mesenchymal cell lineages, we hypothesized that FUS-CHOP-driven sarcomagenesis may be tissue-specific." (PMID 31427882, 2019).
sarcoma (continued). "Thus, we used a third model of FUS-CHOP-driven sarcoma to ask if gene dosage was important for FUS-CHOP-driven transformation." (PMID 31427882, 2019). "These genetically engineered mouse models and novel CRISPR tools will accelerate the study of FUS-CHOP translocation-driven sarcomagenesis and can serve as valuable preclinical models of FUS-CHOP-driven sarcomas to study the response to radiation therapy, chemotherapy, and novel therapeutics." (PMID 31427882, 2019). "No cancer-associated alterations could be detected in teratoma derived from mRNA-derived hiPSCs and only two genes (FUS, NF2) were found altered in Sendai-derived teratoma that were associated with human sarcoma." (PMID 31105870, 2019). "In addition to FUS, the two other members of the FET protein family, Ewing’s sarcoma (EWS) and TATA-binding protein-associated factor 15 (TAF15), have also been found to label a proportion of pathological inclusions in FTLD-FUS." (PMID 30755280, 2019). "Thus, MSC-5H-GFP give rise to pleomorphic undifferentiated sarcomas, meanwhile FUS-CHOP-expressing hBMSCs (MSC-4H-FC, and MSC-5H-FC) initiate MLS-like tumors." (PMID 27105533, 2016). "Next, we investigated whether in vivo ATXN7 accumulation in the nucleus affected two RNA binding proteins: the transactive response DNA binding protein 43-kDa (TDP-43) and the Fused in sarcoma (FUS/TLS)." (PMID 27465358, 2016). "Also RNA-binding protein FUS (fused in sarcoma) is unique and famous for protein regulatory function in transcription and DNA repair activity." (PMID 24910706, 2014). "High-throughput screening has identified at least two RBPs hnRNP A1 and FUS (fused in sarcoma) that bind DRBP76 and might direct alternate RNA switches." (PMID 23976881, 2013). "Thus, ALK likely contributes to the development of FUS/EWSR1-TFCP2 sarcomas and could, in principle, be a therapeutic target." (PMID 38168093, 2024). "Additionally, the EWSR1/FUS::NFATC2 gene rearrangement feature can also be detected in simple bone cysts, but it does not harbour the amplification of the fusion gene and exhibits different clinical manifestations, histology, and prognosis compared to EWSR1/FUS::NFATC2 sarcoma." (PMID 38254207, 2024). "However, the number of studies involving these animal models, including those carrying the transactive response DNA binding protein of 43 kDa (TDP-43), fused in sarcoma (FUS) and C9orf72, are currently too limited to allow a reliable quantitative population study." (PMID 36613659, 2022). "This phenomenon is described in several cases of EWSR1/FUS::NFATC2-rearranged sarcomas in which symptoms were present for years before diagnosis, suggesting that a pre-existing low-grade component may have undergone biological progression in a subset of patients." (PMID 36555836, 2022). "FET (FUS, EWSR1, and TAF15) fusion oncoproteins are characteristic for several sarcomas and leukemias, including myxoid liposarcoma and Ewing sarcoma." (PMID 40988026, 2025). "Only two studies investigated the role of Ewing Sarcoma (EWS) and TAF15 and, which along with FUS constitute the FET family." (PMID 41245603, 2025). "For certain situations, such as EWSR1::POU5F1 sarcoma and rare myoepithelial sarcoma, validation using EWSR1/FUS::NFATC2 fusion probe is necessary." (PMID 38254207, 2024). "This suggests the possibility of EWSR1/FUS::NFATC2 sarcoma and can be validated using EWSR1::NFATC2 or FUS::NFATC2 fusion probe and NGS." (PMID 38254207, 2024). "FUS, also known as Fused in sarcoma (FUS) or Translocated in Sarcoma (TLS), belongs to the FUS/TLS, EWS, and TAF15 (FET) protein family." (PMID 38029395, 2024). "Most cases of FTLD have either transactive response DNA‐binding protein of 43 kDa (TDP‐43; FTLD‐TDP, 50%) or tau inclusions (FTLD‐tau, 45%), with a small number having inclusions of fused in sarcoma (FUS; FTLD‐FUS, <5%)." (PMID 34823271, 2022).
sarcoma (continued). "FET fusion oncoproteins containing one of the FET (FUS, EWSR1, TAF15) family proteins juxtaposed to alternative transcription‐factor partners are characteristic of more than 20 types of sarcoma and leukaemia." (PMID 35182012, 2022). "More than 25 types of sarcoma and leukemia are characterized by fusion oncogenes formed between one of the FET genes (FUS, EWSR1, or TAF15) as 5′ partner and one of more than 30 alternative transcription factor-coding genes as 3′ partner." (PMID 35186752, 2022). "FET family proteins comprising FUS, EWSR1, and TAF15 are not only involved in neurodegenerative disease but also act as oncoproteins in sarcoma or leukemia by chromosomal translocation." (PMID 36194562, 2022). "Significant differences in morphology, transcriptional profile, and behavior are found when comparing sarcomas harboring EWSR1::NFATC2 and FUS::NFATC2 fusions." (PMID 36555836, 2022). "Fusion analysis revealed two FUS::NFATC2 rearrangements in two cystic lesions and three EWSR1::NFATC2 rearrangements in one complex cystic lesion and two sarcomas." (PMID 36555836, 2022). "FUS and EWSR1 belong to the FET group of fusion oncogenes, found primarily in sarcomas and leukemias." (PMID 34068344, 2021). "NFATc2-sarcomas include sarcomas with EWSR1–NFATc2, which commonly show an EWSR1 amplification pattern on fluorescence in situ hybridization, and FUS-NFATc2 fusions." (PMID 33919988, 2021). "FUS and EWSR1, which are the most common fusion partners in translocated fusion oncoproteins and characterize several sarcoma histologies, are drivers of the three-dimensional chromatin structure." (PMID 34299136, 2021). "A protein family consisting of translocated in liposarcoma or fusion in sarcoma (TLS/FUS), Ewing’s sarcoma (EWS), and TAF15 is called the TET (TLS/FUS, EWS, TAF15) family and has various roles in gene expression." (PMID 27181033, 2016). "The FET-protein family comprises FUS (fused in sarcoma, and also abbreviated TLS (translocated in liposarcoma)), EWS (Ewing sarcoma breakpoint region 1, and also abbreviated EWSR1) and TAF15 (TATA box binding protein associated factor 68 kDa)." (PMID 26573619, 2015). "The FUS gene, also known as TLS (translated in sarcoma), was first described as a N-terminal fusion that produced hybrid oncogenes." (PMID 23046583, 2012). "Functional interchangeability of the FET-NTD is also reflected in human sarcomas: both EWS-CHOP and FUS-CHOP characterize myxoid liposarcoma, and EWS-NR4A3 and TAF15-NR4A3 are found in extraskeletal myxoid chondrosarcoma." (PMID 21197473, 2011). "FUS, EWS and TAF15 are structurally similar multifunctional proteins that were first discovered upon characterization of fusion oncogenes in human sarcomas and leukemias." (PMID 18620564, 2008). "All cases were characterised by TAF15 filaments, in the absence of filaments of the other FET proteins, fused in sarcoma (FUS) and Ewing's sarcoma (EWS)." (PMID 41648099, 2026). "Together, these data showed that FUS/EWSR1-TFCP2 transcriptionally activates a core set of genes that include ALK and regulators of muscle physiology, which together may play a role in sarcoma development." (PMID 38168093, 2024). "While FUS fusions are common in some sarcoma subtypes, the TAOK1::FUS fusion has not been previously reported." (PMID 38254244, 2024). "Among the 30 cases with follow-up results, including the four cases reported in our study, the mortality rate of EWSR1/FUS::NFATC2 sarcoma is not high, even though it can exhibit local recurrence and lung metastasis." (PMID 38254207, 2024). "FUS and EWSR1 can replace each other and occur in other sarcomas, while DDIT3 is unique to MLPS." (PMID 36983010, 2023). "This category includes EWSR1/FUS::NFATC2 sarcomas and EWSR1::PATZ1 sarcomas." (PMID 36983010, 2023).